AREG (amphiregulin)
Diseases named in the same sentence as AREG in open-access papers (continued):
Sharing a sentence is not in itself a finding about the gene and the disease.
tumor (continued). "Autocrine stimulation of EGFR by AREG and EREG is a mechanism of tumor EGFR pathway dependence, so the impact of their expression on the response to EFGR-targeted therapy in mCRC patients has also received much attention." (PMID 37974093, 2023). "The eight genes (CAMK2N1, WNT7A, F2RL1, AREG, DEFB1, CNFN, TGFBI, and CAV1) included in the signature have been extensively studied and are known to be involved in tumor progression and EMT process." (PMID 37907576, 2023). "The correlation coefficient between the density of CCL5-positive cells and AREG-positive cells was 0.31, indicating that CCL5 and AREG were present in the tumor microenvironment." (PMID 37553567, 2023). "We identified the cancer cells as the source of HB-EGF and AREG release, despite the fact that macrophages have been previously shown to release EGFR ligands in other tumor types." (PMID 35998057, 2022). "Eosinophils produced matrix metalloproteinases, amphiregulin, TGF-α, or other growth factors in response to tumor-derived GM-CSF." (PMID 36341390, 2022). "Gene set enrichment analysis (GSEA) showed the role of AREG, STAG3 and CAV1 in dysregulated pathways of tumor." (PMID 33712015, 2021). "In the present study, we aimed to assess Amphiregulin, PTEN and P21 expression expression in mCRC patients to correlate their levels of expression with clinicopathological criteria of the tumor and with the outcome of cetuximab sensitivity treatment." (PMID 33906293, 2021). "Gene set enrichment analysis showed the role of AREG, STAG3 and CAV1 in dysregulated pathways of tumor." (PMID 33712015, 2021). "The results revealed that YAP1 is directly connected to secreted AREG, CTGF, CYR61, FGF1 and MSLN that are involved in fibrosis and other key signaling pathways involved in the tumor-stroma interactions." (PMID 32054505, 2020). "AREG and EREG are required for autocrine EGFR signaling, indicating that EREG plays an important role in tumor progression." (PMID 32596278, 2020). "Genes related to oxidative phosphorylation and those related with chemoresistance and poor prognosis such as HNRNPA0, HDAC1, LDHB, AREG, and PSCA were upregulated in subgroups of brain metastasis-derived tumor cells in chemotherapy treated patients." (PMID 33170151, 2020). "In order to determine whether expression of amphiregulin transcript is also upregulated by IL13Rα2, we performed qRT-PCR analyses for the expression of IL13Rα2 and amphiregulin using the cDNAs prepared from tumours originated from SK-MEL-28 and SK-IL13Rα2 cells." (PMID 30718742, 2019). "Of the EGFR ligands, amphiregulin, BTC, EGF, and TGFα were expressed in the cytoplasm of 50%, 76%, 70%, and 73% of the tumours respectively." (PMID 30899442, 2019). "AREG was also upregulated in OPA, and as for AGR2, IHC demonstrated positive labeling for AREG in OPA tumor cells from both natural and experimentally induced disease." (PMID 31434729, 2019). "The level of amphiregulin expression was increased in the tumours originated from the SK-IL13Rα2 cells as compared with those from the SK-MEL-28 cells, suggesting a positive correlation between IL13Rα2 and amphiregulin expressions." (PMID 30718742, 2019). "Of note, when either cetuximab or AREG mAb was co‐administered with MIT as dual agents, tumor showed further reduction in end volume (37.8% and 46.8%, respectively)." (PMID 31493351, 2019). "We have previously shown, consistent with others, that cancer exosomes contain the EGFR ligands, including AREG, suggesting that the EGFR system contributes to the exosome-mediated communication within the tumor microenvironment." (PMID 30621731, 2019). "They showed reduced tumor growth-rate and decreased shedding of the ADAM17 substrates TNFR1-α, AREG, and TGF-α in a xenograft model, upon ADAM17 inhibition." (PMID 29662625, 2018). "Trop2 and amphiregulin (AREG) are both overexpressed in various epithelial cell cancers and have the role in the increases tumor cells division and metastasis." (PMID 28256068, 2017).
tumor (continued). "In fact, the expression of AREG and EREG is coordinately regulated, and plays an important role in tumor growth and survival by generating an autocrine loop through EGFR." (PMID 28002810, 2017). "Tissue and pretreatment serum levels of AREG and EREG protein were negatively correlated with clinicopathological characteristics, such as depth of tumor invasion, distant metastases, and nerve invasion." (PMID 27344184, 2016). "Among patients with RAS WT tumours, ORR was 67% with high AREG expression and 38% with low AREG expression." (PMID 27764839, 2016). "For instance, AREG was shown to activate AKT and ERK pathways, resulting in tumor cell proliferation and the reduced efficacy of trastuzumab treatment." (PMID 27713123, 2016). "Data were analysed by tumour RAS (KRAS/NRAS) and BRAF status, and baseline amphiregulin (AREG) expression." (PMID 27764839, 2016). "Here, we present a retrospective analysis of this first-line trial of panitumumab plus FOLFIRI, reporting efficacy and safety data for first-line FOLFIRI plus panitumumab according to tumour RAS/BRAF status and AREG levels in patients with mCRC." (PMID 27764839, 2016). "Amphiregulin (AREG), a member of the epidermal growth factor family and a rational target for CRC therapy, is essential for the three-dimensional structure of tumor formation." (PMID 25644309, 2015). "The actual mean intensity expression analysis in the clinical prostate database showed that AREG, EREG, and TGFA levels increased in metastatic tumor samples." (PMID 25004126, 2014). "The main differences observed between the two types of hypoxia involved the expression of several genes such as IL-8, CXCL2, EPHA2, AREG, HBEGF, and PLAU, which are relevant to tumor progression." (PMID 25122487, 2014). "In addition, mast cells can induce an immunosuppressive tumor microenvironment by directly enhancing regulatory T cell (Treg) function via mast cell-T cell contact, IL-10, tryptophan metabolism, amphiregulin production, or adenosine, or indirectly by inducing tolerogenic dendritic cells." (PMID 24931643, 2014). "Tumor tissues were stained by immunohistochemistry for VEGF-C, VEGF-D, VEGFR-3, Hif-1 α, PTEN, AREG and EREG expression and evaluated by two independent, blinded investigators." (PMID 25272957, 2014). "Western blot analysis was used to confirm the reduced protein expression of AREG, EREG and DUSP6 in A431 tumour cells stably transduced with AREG-, EREG-, and DUSP6-short hairpin (sh)RNAs." (PMID 22491422, 2012). "In bone metastasis, acting as a sheddase, ADAMTS1 promotes the release of membrane bound epidermal growth factor (EGF)-like growth factors, including amphiregulin (AREG), heparin-binding EGF (HB-EGF), and transforming growth factor α (TGFα) from tumor cells." (PMID 24213506, 2012). "IGROV1-Luc tumour cells in vitro secreted TNF-α, TNFR1-α, TGF-α, AREG, HB-EGF and IL-6Rα, all known substrates for the shedding activity of ADAM17, into the culture medium even when unstimulated." (PMID 22792380, 2012). "AREG and EREG mRNA expression from both the primary tumor and liver metastases were measured using real-time RT-PCR." (PMID 22409860, 2012). "AREG and EREG mRNA expression was strongly correlated in both the primary tumor (Rs = 0.81, p < 0.0001) and the liver metastases (Rs = 0.87, p < 0.0001)." (PMID 22409860, 2012). "In another study, exosomes from breast cancer and colorectal tumors displayed amphiregulin on their surfaces, which engaged with HER1/EGFR on tumor cells to increase their invasiveness." (PMID 22738135, 2012). "High amphiregulin expression has been suggested as a positive predictor of sensitivity to anti-EGFR drugs in NSCLC patients, whose tumour had the P-EGFR gene." (PMID 21750552, 2011). "Ectodomain shedding by the proteases releases three EGF-like factors, HB-EGF, AREG and TGF-α, from tumour cells." (PMID 20010942, 2010).
tumor (continued). "Together, these results provide a rationale for targeting EGF-like factors (HB-EGF, AREG and TGF-α) and proteases (MMP1 and ADAMTS1) in tumour cells, as well as EGFR in osteoblasts for controlling osteolytic bone metastasis of breast cancer." (PMID 20010942, 2010). "Tumour and growth factor genes like WWOX, p73, ITGB4 and AREG were strongly up-regulated by PAR2 activation, supporting roles for PAR2 in proliferation, tumour growth and, perhaps surprisingly, also tumour suppression." (PMID 21072196, 2010). "What is more, lactate plays a critical role in tumour growth and metastasis by promoting angiogenesis through the activation of pathways such as NF-κB, PI3K-AKT-CREB, and HIFs, which upregulate pro-angiogenic factors like amphiregulin (AREG), IL-8, and VEGF." (PMID 41007296, 2025). "In addition, ADAM17 promotes chemotherapy resistance and tumor cell proliferation and survival by shedding EGFR ligands (e.g., Amphiregulin, AREG)." (PMID 41050403, 2025). "AREG is expressed in tumor cells, including breast, colon, and lung, but not in stromal or inflammatory cells and has been implicated in the initiation and progression of tumors." (PMID 40422206, 2025). "While the full MAC assembly can cause cell lysis, sub-lytic MAC deposition—facilitated by elevated C7—activates intracellular pathways in tumor cells, including Ca2+- and G-protein-mediated signals, and transcription factors such as EGR1, IRF1, AREG, and CXCL1." (PMID 40806542, 2025). "AREG, EREG, and VEGFA are angiogenesis-related and often overexpressed in tumor cells." (PMID 40501071, 2025). "Nevertheless, AREG/EREG expression may offer further refinement in selecting candidates for anti-EGFR therapy both in distal and proximal tumor locations and should be evaluated together with genomic negative hyperselection." (PMID 41167084, 2025). "There is a tumor suppressor role for SULF1, being an extracellular sulfatase that removes 6-O-sulfate groups from heparan sulfate (HS) chains, thereby reducing the activity of HS-binding growth factors such as FGF2, VEGF, amphiregulin, HB-EGF, and HGF." (PMID 41373732, 2025). "Intratumoral Treg cells produce high amounts of amphiregulin, which promotes tumor growth without interfering with tumor immune status, probably through the exact mechanism described for lung tissue repair." (PMID 38690280, 2024). "For comparison, another well‐known oestrogen‐regulated gene, AREG, was found in tumours without E2 treatment, especially in GS3, and was up‐regulated by E2 treatment." (PMID 38282415, 2024). "Thus, the AREG/EGFR/HIF-1α signaling pathway contributes to Th9 cell differentiation and anti-tumor function." (PMID 36154925, 2023). "The downregulation of amphiregulin, IL-6 and EPHA2 suggests interference with pathways critical for tumor growth and progression and may explain the pronounced effect seen in the in vivo study." (PMID 37803074, 2023). "Amphiregulin (AREG)/epidermal growth factor receptor (EGFR) signaling induces hypoxia-inducible factor-1α (HIF-1α), leading to promotion of T helper 9 (Th9) differentiation and anti-tumor functions." (PMID 36154925, 2023). "For the prognostic role of tumor EREG/AREG expression in RAS wt patients, no prognostic effect of high versus low expresser status on PFS or OS was seen in the subgroup treated with irinotecan alone." (PMID 37974093, 2023). "This involves molecules such as FGF, HGF, amphiregulin and WNT16B recently identified as components of the SASP in the tumour microenvironment and capable of promoting tumour cell survival/disease progression and attenuating the effects of cytotoxic chemotherapy." (PMID 35177596, 2022). "Additionally, we acquired a total of 6 molecules including IL6, AREG, CXCL12, TGFβ, VEGF and CCL2, which can be upregulated upon senescence, influence immune cell functions, and play tumor-promoting roles in TME30." (PMID 35361903, 2022).
tumor (continued). "Cluster 0 (THBS1+MHClow TAMs) was prevalent in liver, with high expression of THBS1, MARCO and genes promoting the proliferation of EPCs and angiogenesis, such as EREG, AREG, and VEGFA, which could stimulate tumor growth and progression." (PMID 34489408, 2021). "Genes related to cancer pathways were downregulated upon atezolizumab treatment, including angiogenic factors for tumor vascularization (TNK1, AREG and KDR), proto-oncogenes (RET and MET) and tumor cell survival/migration/invasion (CDH1, RARA, WNK2, WNT4A, WNT9A, TGFB2, EGF, and LAMA3)." (PMID 32616706, 2020). "AREG overexpression in CL31 did not affect its tumor growth dynamics in vivo (based on Gluc activity in blood), nor the cells doubling rate in vitro." (PMID 33199705, 2020). "As with EREG, a significant negative correlation was observed between AREG mRNA expression levels and tumor regression (r2 = −0.6, p < 0.001)." (PMID 32674321, 2020). "We also show that inhibition of YAP1/TEAD interaction interferes with the expression of AREG, CTGF, CYR61, and MSLN suggesting that YAP1 transcriptional activity may affect the development and persistence of a fibrotic tumor microenvironment." (PMID 32054505, 2020). "ERBB2-induced gene expression profiles as determined by microarray analysis included cytokeratin 20 (Krt20), Sry-related HMG box gene-17 (Sox17), amphiregulin (Areg), MUC1, and sphingosine kinase 1 (Sphk1) among the genes strongly correlated with tumor growth and metastases of CC cells." (PMID 32708604, 2020). "AREG is a member of the epidermal growth factor (EGF) family and signals through epidermal growth factor receptor (EGFR), notably found on muscle cells and tumor cells including colon, breast, prostate, pancreatic, bladder, ovarian, and melanoma." (PMID 31681327, 2019). "From SOM to EOT, e.g. during tumor progression on single bevacizumab treatment, weak evidence was observed for increase in the level of five proteins (TIMP-4, MMP-8, EGF, Amphiregulin, and Tissue factor/Coagulation factor III), whereas a decrease was seen in only one protein (CD26)." (PMID 30592740, 2018). "However, the cleavage of amphiregulin is mediated by different metalloproteinases such as ADAM17, which is regulated by O2 tension and HIF2, and the latter is related to iron influx in tumor cells." (PMID 29682205, 2018). "The effect of AREG and EREG expression levels in primary tumor samples on the outcome of bevacizumab-treated patients is unknown." (PMID 30467535, 2018). "PyMT expression was absent in ducts and TEBs where AREG was expressed, while AREG expression was rare in hyperplastic and tumor structures in which PyMT staining was present (PyMT panel)." (PMID 30367629, 2018). "From our results using the PyMT mouse model, we found that the absence of AREG changes the tumor histological growth pattern, with AREG−/− tumors developing with more papillary features." (PMID 30367629, 2018). "Low levels of expression of AREG and EREG may characterize a tumor that is less dependent on EGFR and, therefore, particularly prone to develop resistance to EGFR inhibitors." (PMID 28002810, 2017). "Tumor genotype was established using Sequenom Mass ARRAY; EGFR, PTEN, cMET and AXL expression was assessed by immunohistochemistry, circulating markers of EGFR activation (TGF-α, amphiregulin, epiregulin, EGFR ECD) by ELISA and EGFR, MET copy number by FISH." (PMID 27028852, 2016). "Here we report the results of tumor tissue microarray (TMA) analysis in combination with clinical investigation, and evaluate whether testing of AREG expression in GC tissue could be implemented as a predictive, diagnostic, and/or prognostic biomarker in GC." (PMID 27713123, 2016). "AREG staining in most of normal tissues (76.92%) was categorized as “no or low”, and expression was increased in tumor tissue, which was consistent with the AREG mRNA expression data." (PMID 27713123, 2016).
tumor (continued). "Consistent with our in vitro results, tumor growth was significantly suppressed in HSC-6 xenografts without AREG depletion (HSC-6-control groups) with erlotinib treatment (100 mg/kg) compared with vehicle control (p < 0.001)." (PMID 27004400, 2016). "AREG, an epidermal growth factor receptor ligand, is regulated by prolyl-4-hydroxylase domain enzyme 2 (PHD2), a regulator of the stability of HIF-1α that is involved in tumor progression and angiogenesis." (PMID 27435599, 2016). "To investigate whether AREG expression would influence tumor metastasis in vivo, we monitored the metastatic potential of the MG63 cells stably expressing control shRNA or AREG shRNA in mouse models of lung metastasis." (PMID 26503469, 2015). "Among these patients, 69.2% (27/39) HCC tissues were positive for YAP expression in both the nuclei and cytoplasm, whereas 41.0% (16/39) adjacent nontumor tissues were positive for YAP expression; 66.7% (26/39) and 61.5% (24/39) of tumor tissues were, respectively, positive for TAZ and AREG." (PMID 24860833, 2014). "This was accompanied by a minor, barely significant (p = 0.06), negative effect on tumor cell proliferative rate in vivo, with no direct effect of amphiregulin on tumor cell proliferation in vitro." (PMID 24068959, 2013). "The majority of these patients had serum Amphiregulin levels within the normal range and these levels were not significantly altered following tumor removal." (PMID 24010672, 2013). "Monad accelerated the degradation of the pro-invasive gene, amphiregulin, as is the case with TTP, suggesting that Monad may be tumor-suppressive." (PMID 23844004, 2013). "AREG and EREG expression showed a modest correlation between primary tumor and liver metastases." (PMID 22409860, 2012). "We acknowledge that specific knockdown of AREG or EREG expression failed to completely prevent Ctx-induced inhibition of tumour cell growth and survival." (PMID 22491422, 2012). "However, D1(A12) did show clear pharmacodynamic effects in the mice, with significant inhibition of shedding from tumour of ADAM17 substrates TNFR1-α, AREG, and TGF-α (4–15-fold reductions, p<0.0001 for all three)." (PMID 22792380, 2012). "Similarly, several studies have reported an increased efficacy of cetuximab treatment of CRC patients, whose tumour had the WT K-RAS gene and expressed high levels of amphiregulin and/or epiregulin." (PMID 21750552, 2011). "However, EREG and AREG overexpression have still been observed across patient tumors regardless of KRAS BRAF mutational status and primary tumor location." (PMID 40727266, 2024). "However, analysis of matched primary tumor and liver metastases showed EREG and AREG expression levels were not significantly different between the two tumor sites." (PMID 40727266, 2024). "Taken together, while AREG’s role in ovarian pathogenesis and chemoresistance has been established, AREG’s specific effects in the context of the ovarian TIME need to be elucidated, as unraveling its role in HGSOC tumor immunity could lead to novel therapeutic insights." (PMID 36131935, 2022). "In addition, ILC2s express the epidermal-like growth factor Amphiregulin (AREG) that was initially found to mediate proliferation and survival of non-malignant cells, but to limit the growth of tumor cells." (PMID 30999584, 2019). "More importantly, the Kaplan–Meier analysis of PCa patients stratified according to AREG amount in tumor stroma suggested a significant but negative correlation between AREG protein level and disease‐free survival (DFS) in the treated cohort (p < .001, log‐rank test)." (PMID 31493351, 2019). "Although some SASP components are cytokines or chemokines per se, such as IL‐8 and CXCL3, diverse growth factors including amphiregulin (AREG) are produced by senescent human stromal cells, suggesting that the impact of the SASP on tumor progression could be complicated and multidimensional." (PMID 31493351, 2019).